AFP (alpha fetoprotein)
Diseases named in the same sentence as AFP in open-access papers (continued):
Sharing a sentence is not in itself a finding about the gene and the disease.
cancer (continued). "In consideration of other genetic variants more than SNPs in the future will help to learn the true role of AFP levels with genetic correction on the prediction efficiency for cancer risk." (PMID 29696820, 2018). "We also show that partial acquisition of the ESC signature, which occurs later stage of reprogramming, causes the development of cancers that resemble human α-fetoprotein (AFP)-producing cancer." (PMID 29802314, 2018). "Detection of serum alpha-fetoprotein (AFP) is used in clinical follow-up for high-risk population screening and cancer patients." (PMID 29687004, 2018). "In 2012, a first report demonstrated that an RNA aptamer against alpha-fetoprotein (AFP) was able to detect cancer cells, inhibit the proliferation of AFP-associated HepG2 cells and decrease the gene expressions of the c-jun and c-fos oncogenes." (PMID 29416827, 2018). "Combined use of multiple biomarkers is of significance in comprehensive evaluation of AFP-producing GC patients and assessment for those with high risk of cancer recurrence." (PMID 29254216, 2017). "Alpha-fetoprotein elevation has been associated with chronic liver diseases and a limited number of cancers." (PMID 28407756, 2017). "As a demonstration, three different cancer-associated antigens, alpha-fetoprotein (AFP), carcinoembryonic antigen (CEA), and prostate specific antigen (PSA) were chosen as the target analytes." (PMID 28660042, 2016). "This case report is important due to the rarity of the case; furthermore, it provides details of a diagnostic process for a variety of benign diseases and malignant tumors that should be considered in patients with elevated alpha-fetoprotein." (PMID 27246404, 2016). "AFP has a single N-linked oligosaccharide with a biantennary complex-type structure which has altered terminal sialylation and core fucosylation during cancer." (PMID 26509158, 2015). "Moreover, certain factors, such as performance status, smoking history, and elevated AFP levels, were strongly associated with higher agrin levels among cancer patients." (PMID 39123447, 2024). "High AFP levels are associated with poor prognosis and high mortality rates in cancer patients." (PMID 39135041, 2024). "Although the focus of our studies was the β-catenin-CEGRs/ALCDs pathway, it is likely that the promoters of cancer-associated genes, such as the AFP gene, have TCF4 binding sites and may be activated by β-catenin without the assistance of CEGRs/ALCDs." (PMID 36551548, 2022). "AFP is intimately associated with cell proliferation and cancer progression." (PMID 35158917, 2022). "High AFP levels were associated with highly aggressive cancer and correlated with poor prognosis." (PMID 35585534, 2022). "Nine results of AFP were only available with subgroup I patients among 18 patients in this retrospective study (as they may be considered as low-risk patients for cancer liver)." (PMID 34777864, 2021). "HCC cells from 5 to 6 patients and the primary hepatocytes were stained with CK-18, ALB, ARG-1 (biomarkers of hepatocyte and hepatocarcinoma cells) and AFP (biomarker of hepatocarcinoma cells), with cancer-associated fibroblasts (CAFs, from HCC sample) as the negative control." (PMID 34776939, 2021). "For our AFP-secreting HCCs in our cirrhotic subset, the actual outcomes were better when they were only serologically detectable outside the ultrasonic detection range in which cirrhotic patients, albeit more cancer-susceptible, were more often found." (PMID 32845895, 2020).
cancer (continued). "Interestingly, this study found that higher serum IL-13 levels and higher serum AFP levels were associated with cancer (OR = 1.625, 95% CI = 1.077–2.451, p = 0.021) and (OR = 8.231, 95% CI = 2.668–25.394, p < 0.001) respectively." (PMID 32283835, 2020). "Furthermore, we revealed that the reactivation of AFP during hepatocarcinogenesis causes cancer cells to escape Fas/FADD-mediated apoptosis." (PMID 33009373, 2020). "Therefore, it is proposed that oxidative stress can combine hepatic AFP generation, cerebral degeneration as well as higher cancer predisposition in AT children." (PMID 31611883, 2019). "Detection of cancer-specific TERT mutations in patients with low serum AFP may thus complement the AFP assay which has insufficient sensitivity and specificity for early diagnosis of HCC." (PMID 27056898, 2016). "Of these markers the FDA has approved only three as diagnostic cancer antigens: alpha-fetoprotein, CEA, and PSA (approved May 31, 1988, October 15, 1980 and February 25, 1986 respectively)." (PMID 19690635, 2007). "Among the 33 cancers, the RANBP3L expression was linked to the LIHC patients' OS and DSS and further correlated with AFP levels and pathological grade." (PMID 41457788, 2026). "In contrast to MDMs, AFP showed poorer power to differentiate between cancer cases and LC/HVI (p = 0.0029)." (PMID 40135830, 2025). "Targeted delivery was achieved through a human alpha fetoprotein (AFP)-promoter, enabling selective expression and subsequent cancer cell killing upon activation with the prodrug ganciclovir." (PMID 40520550, 2025). "This provides a foundation for the effective utilization of AFP in future treatments and explores new approaches for cancer therapy." (PMID 40430002, 2025). "The activation of growth signaling and the inhibition of apoptotic signaling by AFP promote cancer cell proliferation and metastasis." (PMID 39714631, 2025). "The proposed approach provides a sensitive and scalable strategy for AFP detection, with strong potential for early-stage cancer diagnostics." (PMID 41002370, 2025). "Both treatments markedly reduced serum alpha-fetoprotein levels and alleviated cancer-elated pain, with significant pain score improvements from baseline in each group." (PMID 41357510, 2025). "Specifically, the COMET‐LR and the combination model achieved a favorable sensitivity of 77.6% and 83.6% in stage I cancer cases, superior to AFP (50.7%) and PIVKA‐II alone (68.7%)." (PMID 40135830, 2025). "Despite these limitations, current AFP-targeted therapies remain of interest due to AFP’s critical role in cancer progression." (PMID 40430002, 2025). "In a large comprehensive retrospective study of clinical records in a regional cancer centre, the authors observe moderate and stable elevation of AFP in a significant number of new diagnoses of TCS." (PMID 39934683, 2025). "In this study, we developed a SERS platform based on Au–Ag nanostars for the detection of the cancer biomarker AFP." (PMID 41002370, 2025). "In terms of early detection, the COMET‐LR and the combination model reached a remarkable sensitivity of 82.4% and 85.3% in stage I cancer cases, which outperformed AFP (32.4%) and PIVKA‐II alone (55.9%)." (PMID 40135830, 2025). "Based on these insights, this review aims to comprehensively explore the role of AFP in the development and progression of cancer, highlight the biological functions of AFP and related pathways, and discuss the clinical implications of AFP-targeted therapies." (PMID 40430002, 2025). "This bacterium was also found to be negatively correlated with alpha-fetoprotein, a cancer biomarker involved in gastrointestinal cancers." (PMID 40153368, 2025). "These various attempts to target AFP are expected to improve treatment outcomes, minimize side effects, and improve the quality of life of cancer patients." (PMID 40430002, 2025).
cancer (continued). "Ongoing research on AFP will significantly contribute to our understanding of the biological mechanisms of cancer and aid in developing effective and safe treatments." (PMID 40430002, 2025). "We included the protein biomarkers, HE4, CA19-9, CEA, and AFP, which are all commonly used in clinical cancer detection, as well as prolactin (PRL) and interleukin-6 (IL-6), which have been reported in previous studies." (PMID 40502685, 2025). "Detection of serum AFP levels in cancer cells can be monitored in real time for the early diagnosis and treatment of liver cancer to create better conditions." (PMID 40942360, 2025). "Ultimately, advancements in AFP-targeted therapeutic approaches are expected to play a crucial role in the future of cancer management." (PMID 40430002, 2025). "Unlike conventional SERS systems, this aqueous, surfactant-free platform exploits the intrinsic vibrational modes of AFP, enabling sensitive and rapid biomarker detection with strong potential for early cancer diagnostics." (PMID 41002370, 2025). "It’s important to note that patients receiving LRT tended to have more aggressive cancer features before their transplant, such as microvascular invasion and higher alpha-fetoprotein levels." (PMID 40361428, 2025). "Common cancer biomarkers, such as prostate-specific antigen (PSA), carcinoembryonic antigen (CEA), CA 125, CA 19-9, and alpha-fetoprotein (AFP), have been extensively studied for early cancer screening, diagnosis, and monitoring." (PMID 40277545, 2025). "In intermediate-stage HCC, significant differences were observed in age, sex, American Society of Anesthesiologists score, cancer stage, platelet count, AFP levels, microvascular invasion, and liver function-related variables." (PMID 40739081, 2025). "AFP-targeted therapies hold promise for selectively targeting cancer cells expressing high levels of AFP, minimizing damage to healthy cells, reducing side effects, and potentially maximizing the effectiveness of immunotherapy." (PMID 40430002, 2025). "This review explores the role of AFP in cancer development and progression, highlights the biological functions of AFP and related pathways, and discusses the clinical implications of AFP-targeted therapies." (PMID 40430002, 2025). "Histological examination of lymph node biopsies on three separate occasions consistently showed poorly differentiated carcinoma, with two of the samples demonstrating focal positivity for AFP on immunohistochemistry." (PMID 41561743, 2025). "In the current study, PIGR expression was significantly correlated with the clinical phenotype (cancer vs inflammatory lesions; P ═ 0.0006) and AFP (P ═ 0.045)." (PMID 39284282, 2024). "For example, co-cultured umbilical cord-derived MSCs with hepatocarcinoma cell line HepG2 downregulated the protein expression of AFP, Bcl-2, and survivin and accelerated cancer cell apoptosis, which was related to the apoptosis signal pathway." (PMID 38660138, 2024). "Human alpha-fetoprotein (HAFP) has a long history of clinical use as a tumor-associated fetal biomarker, utilized to detect both fetal defects during pregnancy and cancers in adults." (PMID 38672613, 2024). "Serum AFP levels are often elevated in patients with RPTs, particularly in cases involving high-grade immature or malignant tumors." (PMID 39791094, 2024). "Melittin gene was carried by an adenovirus vector containing the hypoxia-response element (HRE)-alpha fetoprotein (AFP) promoter to control adenovirus E1a gene expression to target AFP-positive cancer cells under a hypoxic microenvironment." (PMID 38318188, 2024). "Further innovations in dual-signaling molecules, quantum dots, and RNA binding probes can provide platforms for ultrasensitive and early detection of cancer biomarkers like AFP." (PMID 38999110, 2024).
cancer (continued). "Key findings indicated variations in alpha-fetoprotein levels and increased expression of the immune marker PD-L1 in untreated patients, suggesting a more aggressive cancer progression in these individuals." (PMID 38791994, 2024). "TICRR was found drastically highly expressed in a variety of cancer types including HCC.ROC curve analysis showed that TICRR had higher accuracy in predicting HCC compared with AFP." (PMID 37266876, 2024). "AFP also has a prognostic function and is used to monitor treatment response and detect early cancer recurrence." (PMID 39685591, 2024). "On the contrary, the Cancer of the Liver Italian Program143 and the Groupe d'Etude et de Traitement du Carcinome Hépatocellulaire staging from France144 included alpha‐fetoprotein (AFP) as a biomarker." (PMID 38590119, 2024). "Our findings showed that serum IL-41 expression was significantly correlated with micro-vascular invasion(MVI), poorly differentiated cancer cells, and high preoperative AFP." (PMID 38835390, 2024). "These two cancer cells can achieve cohesion in a short time, express AFP and have HBV DNA, and retain highly specific genetic changes." (PMID 39192365, 2024). "Although expressed at minimal levels in adults, elevated AFP levels can indicate certain pathological conditions involving liver regeneration, hepatitis, or cancer." (PMID 39767676, 2024). "Alpha-fetoprotein (AFP) is considered one of the best-known predictive serum markers, playing a crucial role in cancer investigation and subsequent treatment." (PMID 38817451, 2024). "Clinically, AFP is considered one of the best-known predictive serum markers and is an essential and common target in cancer investigation and subsequent treatment." (PMID 38817451, 2024). "Further studies are needed to assess the safety and effectiveness of this approach in multi-agent chemotherapy, emphasizing AFP as a potential biomarker for the development of targeted cancer therapies." (PMID 39135041, 2024). "In the context of liver transplantation, AFP is also recognized as a marker of HCC biology, and clinical trials have been conducted on a cancer vaccine utilizing an AFP-derived class I-restricted epitope as the antigen." (PMID 39286027, 2024). "The authors found that nerve fiber expression within the tumors was significantly correlated with alpha-fetoprotein (AFP) serum level, clinical stage, and cancer recurrence." (PMID 38892423, 2024). "Studies have reported that AFP can influence the ability of cancer cells to maintain and propagate their undifferentiated, stem-like state." (PMID 39583507, 2024). "The results showed that AFP-CAR T effectively eliminated AFP-expressing cancer cells in mouse models, highlighting the potential of this strategy for treating solid tumors that are resistant to traditional therapies." (PMID 39685591, 2024). "The intricate interplay between AFP and HSP90, impacting the stability of critical oncogenic proteins, sheds light on potential therapeutic targets for AFP-associated cancers." (PMID 39135041, 2024). "Although AFP-L3 levels are correlated with AFP levels, AFP-L3 shows higher specificity than AFP because AFP-L3 is derived from cancer cells." (PMID 39330520, 2024). "AFP also activates these signaling pathways to promote the malignant transformation of cancer cells." (PMID 38660138, 2024). "Owing to the presence of specific AFP-receptors in certain cancer cells, AFP has shown more promising potential for targeted drug delivery in cancer treatment than HSA." (PMID 38678117, 2024). "AED is a carcinoma with tubulopapillary growth of columnar cells with clear cytoplasm expressing oncofetal proteins, including AFP, GPC3, and/or SALL4." (PMID 38851063, 2024). "These systems have successively been developed and have shown potential for detecting clinically relevant targets, such as cancer biomarkers, including AFP, CEA, and PSA." (PMID 37298550, 2023).
cancer (continued). "In order to verify the universality of the platform, three cancer biomarkers (alpha‐fetoprotein, carcinoembryonic antigen, carbohydrate antigen 125) are selected for quantitative detection." (PMID 37358326, 2023). "In the presence of AFP, cancer cells grow faster and can form cancer bolts by invading the vasculature, resulting in distant metastasis." (PMID 37161409, 2023). "Subsequently, the anti-AFP antigen (cancer marker) and anti-AFP polyclonal antibody composite MGITC-HGN (functional nanoprobe) were injected into entrance B and C in turn, flowing downward and used to form sandwich immune complex on gold pattern microarray." (PMID 37149605, 2023). "A biomarker signature based on HDA, DHK-PGA2, and AFP showed great diagnostic efficacy in diagnosing T2DM(+) HCC from T2DM and other T2DM(+) cancers, including GC, PC, and CRC, suggesting its potential for clinical application." (PMID 36677015, 2023). "Alone or combined with alpha-fetoprotein, metabolite and lipid signatures can serve as a powerful approach for screening cancer progression and timely diagnosis." (PMID 37999208, 2023). "Although PGCCs in some cancers have been reported to exhibit stem cell features, PGCCs positive for the oncofetal protein AFP was relatively rare among polyploid HCCs." (PMID 37715023, 2023). "In this construct, the hypoxia-response element (HRE)-AFP promoter is employed to regulate viral E1a expression, specifically targeting AFP-positive cancer cells; additionally, the E1b-55 kDa gene has been removed." (PMID 38133203, 2023). "As a cancer biomarker, AFP is classified as an oncofetal glycoprotein, having a molecular weight of 70 kDa approximately." (PMID 37232911, 2023). "The recoveries of AFP in human serum were around 108%, providing a wonderful strategy for fast, sensitive, and accurate cancer diagnosis." (PMID 37232911, 2023). "A sandwich-type immunoassay for alpha fetoprotein (AFP) cancer biomarkers was fabricated with GSH-AuPt NCs as signal tags, which displayed a wide linear range from 0.01 to 1000 ng·mL−1 and a limit of detection (LOD) down to 1.0 pg·mL−1 at 3S/N." (PMID 37232911, 2023). "After treating cancer mice with SS-b2, the serum levels of alpha-fetoprotein, aspartate aminotransferase, alanine aminotransferase, and lactate dehydrogenase significantly reduced." (PMID 37893233, 2023). "In the treatment of HCC as well as other cancers, AFP and its receptor can act as both a target and a drug." (PMID 36768863, 2023). "In clinical practice, AFP biomarker is often utilized for cancer diagnosis, although its reported sensitivity in cancer detection is quite low." (PMID 37936230, 2023). "In this study, a QCM immunosensor based on the design to contact serum on one side only was successfully developed for the determination of AFP from serum samples that were obtained from cancer patients." (PMID 37175021, 2023). "The article presents the role of alpha-fetoprotein in the diagnosis and monitoring of treatment for selected genetic diseases and early childhood cancers." (PMID 37686577, 2023). "Data from the Children’s Oncology Group(COG) and the Children’s Cancer and Leukemia Group have proven high AFP levels to be a poor prognostic factor." (PMID 38001671, 2023). "Carcinoembryonic antigen (CEA) and alpha-fetoprotein (AFP) are well-studied oncofoetal antigens that are expressed at high levels in cancer cells and foetal tissues." (PMID 36836537, 2023). "The combination of AFP with toxins destroys cancer cells (chemotherapy) and stimulates the immune response of T and NK: natural killer lymphocytes (immunotherapy)." (PMID 36768863, 2023). "Many biomarkers associated with cancer have been found and can be used for cancer diagnosis, such as carcinoembryonic antigen (CEA), alpha-fetoprotein (AFP), prostate-specific antigen (PSA), carbohydrate antigen (CA), neuron-specific enolase (NSE), etc." (PMID 37177441, 2023).